CNOT11 (CCR4-NOT transcription complex subunit 11)
Description:
Component of the CCR4-NOT complex which is one of the major cellular mRNA deadenylases and is linked to various cellular processes including bulk mRNA degradation, miRNA-mediated repression, translational repression during translational initiation and general transcription regulation. Additional complex functions may be a consequence of its influence on mRNA expression. Is required for the association of CNOT10 with the CCR4-NOT complex. Does not seem to be required for complex deadenylase function.
Synonyms: C2orf29; C40
Tractability: PROTAC: ubiquitination databases record sites on it; its protein half-life has been measured.
Gene: Protein-coding gene on chromosome 2 (101,252,873 to 101,270,316, forward strand). Ensembl gene ENSG00000158435.
Subcellular location: Cytoplasm; Nucleus
Subcellular location (Human Protein Atlas): Nucleoplasm
Pathways (Reactome):
Developmental Biology: M-decay: degradation of maternal mRNAs by maternally stored factors
Metabolism of RNA: Deadenylation of mRNA
Gene Ontology:
Molecular function: protein binding
Biological process: nuclear-transcribed mRNA poly(A) tail shortening
Cellular component: CCR4-NOT complex; cytosol; cytoplasm; nucleus
Genetic constraint (gnomAD): Loss-of-function variants: 12 observed, 33.36 expected, observed/expected ratio (o/e) 0.36, 90% interval 0.23 to 0.58. The upper end of that interval is the gene's LOEUF score, 0.58, which puts it in group 2 of 6, group 1 being the genes least tolerant of losing a copy. Missense variants: 493 observed, 604.04 expected, observed/expected ratio (o/e) 0.82, 90% interval 0.76 to 0.88. Synonymous variants: 276 observed, 243.15 expected, observed/expected ratio (o/e) 1.14, 90% interval 1.03 to 1.25.
Homologues: Orthologues: chimpanzee CNOT11 (99% identical), macaque CNOT11 (99% identical), dog CNOT11 (99% identical), pig CNOT11 (97% identical), mouse Cnot11 (95% identical), rat Cnot11 (95% identical), guinea pig CNOT11 (95% identical), tropical clawed frog cnot11 (82% identical), zebrafish cnot11 (75% identical), Drosophila melanogaster Not11 (26% identical), Caenorhabditis elegans ntl-11 (17% identical).
Diseases named in the same sentence as CNOT11 in open-access papers:
CNOT11 is named in the same sentence as 7 diseases in open-access papers, as found by Europe PMC text mining. Sharing a sentence is not in itself a finding about the gene and the disease. The quoted sentences say what the papers report.
genetic diseases (1 paper, 2023). "The findings assign molecular functions to the previously obscure proteins SCAPER and CNOT11, provide mechanistic insight into genetic diseases caused by SCAPER mutations, and provide a detailed view of how a nascent protein can selectively control the degradation of its encoding mRNA." (PMID 37295431, 2023).
CNOT11 also shares sentences with these, for which no sentence is quoted: atopic dermatitis (1 paper); lung carcinoma (1); metabolic disorders (1); parasitemia (1); Pc (1); tumor (1).